CCN1 (cellular communication network factor 1)
Diseases named in the same sentence as CCN1 in open-access papers (continued):
Sharing a sentence is not in itself a finding about the gene and the disease.
atherosclerosis (19 papers, 2014 to 2025). A disease characterized by the build-up of fatty material and calcium deposition in the arterial wall resulting in partial or complete occlusion of the arterial lumen. "Prior studies have implicated Ccn1 in pathological vascular remodeling, fibrosis, and atherosclerosis." (PMID 41026613, 2025). "Additionally, CCN1 has been linked to a few clinical conditions, such as cancer, atherosclerosis, arthritis, and fibrosis." (PMID 38478501, 2024). "Disruptions in serum CCN1 levels are associated with subclinical atherosclerosis in RA patients." (PMID 36249997, 2022). "Knock-in mice (Ccn1dm/dm/Apoe−/−) carrying a mutant Ccn1 allele unable to bind integrin α6β1 exhibit reduced plaque formation, suggesting the importance of CCN1 and integrin α6β1 interaction in atherosclerosis development." (PMID 41300494, 2025). "The YAP/TAZ target CCN1 enhances atherosclerosis through tension-driven engagement of α6β1 integrin to activate downstream NFκB." (PMID 39507419, 2024). "Later, CCN1 was also found to participate in pathological processes, including but not limited to arthritis, fibrosis, atherosclerosis, and cancer." (PMID 33105556, 2020). "In atherosclerosis diseases, the increased expressions of the CCN1 and CCN2 were also found where the inflammatory cells accumulated, practically around the plaques." (PMID 33105556, 2020). "CCN1 is also up-regulated in rodent models of myocardial infarction, atherosclerosis, diabetic retinopathy, hypertension and most importantly for this study, angioplasty restenosis." (PMID 25446180, 2015). "Elevated CCN1 levels contribute to endothelial dysfunction and promote atherosclerosis." (PMID 41300494, 2025). "Collectively, existing literature suggests that novel approaches targeting CCN1 expression or secretion may hold therapeutic potential for treating atherosclerosis by attenuating endothelial dysfunction, foam cell formation, and hepatic lipid accumulation." (PMID 41300494, 2025). "In Apoe−/− mice, CCN1 treatment exacerbates atherosclerosis and induces systemic inflammation." (PMID 41300494, 2025). "CCN1 is strongly associated with NAFLD-related diseases such as diabetes and atherosclerosis." (PMID 36145246, 2022). "These functional and mechanistic observations could open a new avenue to further explore their therapeutic potential for treating post-angioplasty restenosis and atherosclerosis by targeting Cezanne/β-catenin/CCN1 signalling axis." (PMID 33599243, 2022). "Not only has been reported that CCN1 plays a pivotal role in regulating cholesterol metabolism and the development of atherosclerosis, but there is increasing evidence that CCN1 participates in the development and progression of various cardiovascular diseases." (PMID 33906697, 2021). "Among them, CCN1/CYR61 is the most well-characterized example of how matricellular proteins may regulate the formation of atherosclerosis." (PMID 33889574, 2021). "In addition to known proatherogenic genes, our RNA-Seq analysis identified 2 potentially new proatherogenic genes, Ccn1 and Ccn2, that may contribute to increased atherosclerosis in F1 females." (PMID 39253968, 2024). "Thus, it is plausible that the increased endothelial Ccn1/Ccn2 expression may affect other cell types such as macrophages to contribute to the exacerbated atherosclerosis in F1 female mice from HCD-fed sires." (PMID 39253968, 2024). "Additionally, CCN1-α6β1 engagement is proven a promising therapeutic target for atherosclerosis." (PMID 33889574, 2021). "This blocked the expression of its subsequent atherogenic target CCN1 and verified that JCAD encourages endothelial malfunction, inflammation, and atherosclerosis." (PMID 39507419, 2024).
atherosclerosis (continued). "To elucidate the potential role of CCN1 and CCN2 in regulating endothelial cell function related to atherosclerosis, we treated human endothelial cells, HMEC-1 cells, with recombinant human CCN1 or CCN2 proteins." (PMID 39253968, 2024). "CCN1 and CCN2 have been reported to be highly expressed in aortic atherosclerotic plaques of a mouse model of atherosclerosis and human atherosclerotic lesions." (PMID 24722330, 2014). "We aimed to explore the effect of the overexpression of CCN3 on CCN1 and CCN2 levels in atherosclerosis." (PMID 24722330, 2014). "In the present study, we observed that the overexpression of CCN3 downregulated gene expression of CCN1 and CCN2, indicating that the three CCN proteins had positive or negative effects in atherosclerosis." (PMID 24722330, 2014).
hepatocellular carcinoma (18 papers, 2010 to 2025). A malignant tumor that arises from hepatocytes. "However, another report has demonstrated that CCN1 expressed by HSC is involved in the progression from cirrhosis to hepatocellular carcinoma (HCC) through promoting the growth and proliferation of HCC." (PMID 37166689, 2023). "Moreover, despite conflicting reports regarding the role of CCN1 in hepatocarcinogenesis, CCN1 has been suggested to suppress hepatocellular carcinoma by inhibiting carcinogen-induced compensatory hepatocyte proliferation through integrin α6β1." (PMID 27167338, 2016). "We previously showed that CCN1 is a direct target of β-catenin signaling in hepatocellular carcinoma (HCC), where it may be important for cancer progression." (PMID 25187756, 2014). "The role of CCN1 in hepatocellular carcinoma is controversial." (PMID 25187756, 2014). "The matricellular protein CCN1 (CYR61/CCN1, cysteine-rich protein 61) inhibits EGFR-dependent hepatocytes proliferation through ROS accumulation induced by α6β1 integrin in liver carcinoma." (PMID 26635609, 2015).
colon carcinoma (15 papers, 2010 to 2025). "We identified seven EMT-related genes (TPM1, LAMC1, POSTN, CCN1, MGP, PCOLCE2, and DPYSL3) with prognostic significance in patients with colon cancer from TCGA and GSE17536 cohorts." (PMID 34180352, 2021).
diabetes (13 papers, 2008 to 2024). "Although CCN1 is closely associated with DR, there are few studies on blood CCN1 levels in patients with diabetes." (PMID 37334311, 2023). "We found that BMI, duration of diabetes, and urea levels were associated with CCN1 expression, but these correlations were weak." (PMID 37334311, 2023). "In patients with diabetes, very high blood CCN1 levels were associated with an increased risk of DR (OR 5.91, 95% CI: 2.12–16.49)." (PMID 37334311, 2023). "CCN1 expression was also upregulated in the retinas of NOD mice that had spontaneously progressed to diabetes (random blood glucose levels exceeding 16.7 mmol/L) when compared to their diabetes-free littermates." (PMID 38755602, 2024). "By performing linear correlation analysis of CCN1 and other clinical indicators, we found that CCN1was positively correlated with diabetes durations, NLR, and neutrophils count." (PMID 38755602, 2024). "In this study, we delved into the intricate interplay between CCN1 and neutrophils and examined their roles in exacerbating retinal leakage in the context of diabetes." (PMID 38755602, 2024). "CCN1 levels negatively correlated with body mass index and positively correlated with the duration of diabetes and urea levels." (PMID 37334311, 2023). "CCN1 levels negatively correlated with BMI (r = –0.359, p< 0.001) and positively correlated with the duration of diabetes (r = 0.370, p< 0.001) and urea levels (r = 0.206, p = 0.041)." (PMID 37334311, 2023). "CCN1 was negatively correlated with BMI and positively correlated with the duration of diabetes and urea levels." (PMID 37334311, 2023). "As a regulator expressed in myofibroblasts preventing fibrosis through induction of cellular senescence, CCN1 mRNA was unchanged in the CHOW fed diabetes alone group, whereas it was induced in the HFD alone model." (PMID 35038159, 2022). "To explore the molecular mechanism by which MOTS-c improves cardiac function in diabetes, we performed transcript analysis of the highly expressed CCN1, ERK1, ERK2, and EGR1 genes by qRT-PCR." (PMID 36687680, 2022). "Notably, both CCN1 knockdown and DNase I treatment rescued the retinal leakage in the context of diabetes." (PMID 38755602, 2024). "Furthermore, we validated the expression of CCN1 in publicly available single-cell sequencing (scRNA-Seq) data of retinas from various diabetes models." (PMID 38755602, 2024). "Interestingly, our results showed that the expression level of CCN1 in the retina of mice with diabetes was significantly higher than that of control mice." (PMID 34458333, 2021). "In addition to hypoxia, CCN1 expression in rat retinas is increased by more than 3-fold after 6 weeks of diabetes, and increased by 4-fold in the advanced glycation end product (AGE)-treated mouse retina." (PMID 34458333, 2021). "Prior research has delved into the association of various members of the CCN family (ranging from CCN1 to CCN6) with metabolic disorders, encompassing conditions such as obesity, diabetes, insulin resistance, and non-alcoholic fatty liver." (PMID 37919772, 2023). "A previous study has unveiled elevated CCN1 levels in the vitreous humor of DR patients when compared to individuals without diabetes-related ocular conditions." (PMID 38755602, 2024). "Notably, circulating CCN1 was positively correlated with several key clinical parameters, including the absolute neutrophil count, NLR, NE, and the duration of diabetes." (PMID 38755602, 2024). "Studies on the comparison of the blood CCN1 levels in patients with diabetes and healthy individuals and the relation between blood CCN1 levels and DR have not been reported." (PMID 37334311, 2023). "Circulating NE was positively correlated with CCN1, HbA1c, FBG, DM duration, and TG, thereby supporting the potential role of NE in the pathology of diabetes." (PMID 38755602, 2024).
diabetes (continued). "Plasma CCN1 levels were detected using ELISA in 50 healthy controls, 74 patients with diabetes without diabetic retinopathy (DM group), and 69 patients with diabetic retinopathy (DR group)." (PMID 37334311, 2023). "The CCN2Ab did not have effects in the diabetes nor in HFD alone groups, and it showed only a trend towards lowering CCN1 in the HFD + DM model." (PMID 35038159, 2022). "However, in this diabetes model, exercise training does not upregulate CCN1/CYR61 nor does restore capillarization in type-I diabetic mice." (PMID 34063397, 2021).
ovarian carcinoma (13 papers, 2014 to 2025). A malignant neoplasm originating from the surface ovarian epithelium. "Furthermore, overexpression of CCN1 can inhibit carboplatin-induced apoptosis by decreasing Bax expression and increasing Bcl-xL, Mcl-1, and Bcl-2 levels in ovarian cancer cells." (PMID 40234387, 2025). "Previous studies have shown that CCN1 activates ERK in ovarian carcinoma cells and osteoblasts." (PMID 25187756, 2014). "Our results demonstrate that S1P disrupts Hippo signaling by reducing YAP phosphorylation and increasing the expression of CCN1 and CCN2 in both ovarian cancer cells." (PMID 28460443, 2017). "To further investigate the roles of CCN1 and CCN2 in the S1P-induced cell proliferation, we used small interfering RNA targeted knock down approach in two ovarian cancer cell lines." (PMID 28460443, 2017). "Given the important roles of S1P and Hippo signaling pathway in the tumorigenesis of ovarian cancer, we sought to investigate the effects of S1P on YAP and its downstream effectors CCN1 and CCN2 genes." (PMID 28460443, 2017). "However, inconsistent with these results, our previous studies showed that both CCN1 and CCN2 mediate the cellular action downstream of S1P in ovarian cancer cells." (PMID 31731760, 2019). "In ovarian cancer cells, S1P functions as an upstream stimulator of the Hippo signaling pathway to promote cell proliferation by inducing nuclear accumulation of YAP followed by upregulation of CCN1 and CCN2." (PMID 31731760, 2019). "Our in vitro results suggest that S1P and CCN1/CCN2 may play crucial roles in the development and progression of ovarian cancers." (PMID 28460443, 2017). "To date, the fundamental role of CCN1 and CCN2 in the development of ovarian cancers remains unclear." (PMID 28460443, 2017). "Consistent with these clinical data, our experimental results showed that knockdown of the endogenous CCN1 and CCN2 significantly decreased the cell proliferation in EOC cells, indicating that CCN1 and CCN2 might play a pivotal role in the progression and outcome of ovarian cancers." (PMID 28460443, 2017).
triple-negative breast carcinoma (11 papers, 2015 to 2024). An invasive breast carcinoma which is negative for expression of estrogen receptor (ER), progesterone receptor (PR), and human epidermal growth factor receptor 2 (HER2). "We show that co-incubation of triple-negative breast cancer (TNBC) cell line MDA-MB-231 with human pulmonary microvascular endothelial monolayers (HPMEC) secretes Cyr61 (CCN1), primarily from MDA-MB-231." (PMID 31824306, 2019). "Taken together, we have demonstrated for the first time that co-incubation of triple-negative breast cancer cell line MDA-MB-231 with HPMEC promotes the secretion of Cyr61 (CCN1), primarily from MDA-MB-231, which forms Cyr61/integrin αvβ1 complex." (PMID 31824306, 2019). "We have previously shown that the matricellular CCN1 (CYR61) promotes the lung metastasis of triple negative breast cancer (TNBC) cells by binding to active β1 integrin at the cell surface and promoting AMP-activated protein kinase α (AMPKα) signaling, survival, and early colonization of the lung." (PMID 31336983, 2019). "CCN1 protein levels in MCF-7/CCN1, MCF-7/D125A-CCN1, and MCF-7/TM-CCN1 cells were comparable to those of MDA-MB-231 cells, a triple-negative breast cancer model naturally overexpressing CCN1." (PMID 35148282, 2022).
Arthritis (10 papers, 2005 to 2024). Inflammation of a joint. "This current study indicated that CCN1 mediates arthritis pathogenesis and supports the previous evidence suggesting that CCN1 plays a critical role in autoimmune/inflammatory diseases." (PMID 28341837, 2017). "Results show CCN1 up-regulating OSM expression via αvβ3 receptor FAK/c-Src/PI3K/NF-κB signal pathway, lending insight into CCN1’s therapeutic value against arthritis." (PMID 25187949, 2014). "Results indicate CCN1 heightening OSM expression via αvβ3 receptor, FAK, c-Src, PI3K, and NF-κB signal pathway in osteoblastic cells, suggesting CCN1 as a novel target in arthritis treatment." (PMID 25187949, 2014). "CCN1 has been shown to stimulate abnormal proliferation and play a critical role in arthritis pathogenesis." (PMID 25187949, 2014). "CCN1 promotes fibroblast-like synoviocytes proliferation and activates Th17 cells in arthritis pathogenesis." (PMID 25187949, 2014). "Genomic studies show CCN1 strongly expressed in collagen-induced arthritis in rodents, suggesting CCN1 inhibitor reduces inflammatory response." (PMID 25187949, 2014). "In this study, we comparatively analyzed the expression profiles of ccn1 and ccn2, while simulating the course of arthritis; i.e., inflammation, tissue regeneration and anti-inflammatory treatment, utilizing a human chondrocytic HCS-2/8." (PMID 15833111, 2005). "In vitro simulation of arthritis with a human chondrocytic cell line revealed the same response pattern of ccn1 as that of ccn2, which is known as a regenerative mediator in cartilage repair." (PMID 15833111, 2005). "In contrast, inhibition of CCN1 expression with lentiviral vectors expressing short hairpin RNA ameliorated articular swelling, cartilage erosion, and infiltration of monocytes in the ankle joints of mice with collagen-induced arthritis." (PMID 28341837, 2017). "Next, we used the CIA model to investigate whether the knockdown of CCN1 was able to inhibit arthritis in vivo." (PMID 28341837, 2017). "Earlier study described CCN1 regulating IL-6 expression during arthritis process." (PMID 25187949, 2014). "Prior studies indicated CCN1-activated integrin receptor applying to arthritis: binding of CCN1 to αvβ5 or α6β1 could promote cell apoptosis and reactive oxygen species generation." (PMID 25187949, 2014). "Previous study correlated arthritis with heparin-binding protein, CCN1." (PMID 25187949, 2014).
lung fibrosis (10 papers, 2012 to 2024). "After that, they demonstrated through a number of experimental investigations that CCN1 causes lung fibrosis by boosting the expression of the TGF-1β/Smad 3 pathway." (PMID 38478501, 2024). "Elevated CCN1 in response to lung injury induced profibrotic gene expression via the TGF-β1/SMAD3 pathway leading to lung fibrosis." (PMID 33105556, 2020). "More studies are required to address this discrepancy and identify the exact role of CCN1 in progressive lung fibrosis in vivo." (PMID 33105556, 2020). "CCN1, a member of the CCN family of matricellular proteins, has similar in vitro functions to CCN2 and is associated with lung fibrosis." (PMID 29049376, 2017). "In addition, CCN1 has been shown to play a role in the development of various lung diseases, such as pulmonary fibrosis." (PMID 37887075, 2023). "However, the data obtained from various studies have generated much debate regarding the profibrotic or antifibrotic effects that CCN1 may exert on the development of pulmonary fibrosis." (PMID 37887075, 2023). "The cellular matrix protein cyr61 (CCN1), a multifunctional matricellular protein dynamically involved in ECM remodeling, enhances TGFβ1/SMAD profibrotic signaling in fibroblasts and contributes to lung fibrosis and angiogenesis." (PMID 33462282, 2021). "Similarly, in a bleomycin-induced experimental ALI in mice, CCN1 expression was found to be elevated in the alveolar mesenchymal cells, which in turn, activated the TGF-b1/SMAD3 pathway-dependent profibrotic signaling that contributed to ALI-mediated pulmonary fibrosis." (PMID 33105556, 2020).
Nephroblastoma (10 papers, 2010 to 2024). An embryonal neoplasm characterized by the presence of epithelial, mesenchymal, and blastema components. "The Cyr61/CCN1 gene encodes a matricellular protein that belongs to the CCN family comprising CCN1/Cyr61; CCN2/CTGF (connective tissue growth factor); CCN3/NOV (nephroblastoma overexpressed); and CCN4-6/WISP1–3 (Wnt-inducible secreted proteins)." (PMID 20195466, 2010). "The abbreviation CCN stems from the initial three members of this family: CYR61 (CCN1), CTGF (CCN2), and NOV (nephroblastoma overexpressed/CCN3)." (PMID 38542515, 2024). "The CCN family includes CCN1/CYR61 (cystein-rich 61], CCN2/CTGF (connective tissue growth factor), CCN3/NOV (nephroblastoma overexpressed), and also CCN4/WISP-1, CCN5/WISP-2, CCN6/WISP-3 (Wnt-inducible secreted proteins)." (PMID 34940056, 2021). "The family members other than CTGF are cysteine-rich angiogenic inducer 61 (Cyr61/CCN1), nephroblastoma overexpressed genes (Nov/CCN3), and Wnt-inducible signaling pathway proteins 1–3 (WISP1-3/CCN4-6)." (PMID 30123390, 2018). "The name of the family is an acronym of the first three identified members, namely CYR61 (CCN1), CTGF (CCN2) and the Nephroblastoma-overexpressed gene (NOV, CCN3)." (PMID 21209863, 2010).